BDNF (brain derived neurotrophic factor)
Diseases named in the same sentence as BDNF in open-access papers (continued):
Sharing a sentence is not in itself a finding about the gene and the disease.
depression (continued). "Stress-associated anxiety-like phenotypes, which may coexist with depression-like phenotypes, were also demonstrated to be related with the reduction of BDNF in the hippocampus." (PMID 32085670, 2020). "The brain-derived neurotrophic factor (BDNF) Val66Met (substitution of valine (Val) to methionine (Met) at codon 66) polymorphism has been shown to be associated with executive functions as well as depression." (PMID 32002751, 2020). "Moreover, the same authors in a second paper showed that the high methylation levels of BDNF promoter region were independently associated with post-stroke depression and with a worsening of depressive symptoms during follow-up." (PMID 33182716, 2020). "For instance, female mice with BDNF deletions in the forebrain or hippocampus are more sensitive to chronic unpredictable stress and exhibit depression-like behaviors; on the contrary, loss of BDNF in the same brain regions does not increase stress susceptibility in male mice." (PMID 32085670, 2020). "It has been assumed that BDNF is implicated in the etiology of depression and ADs." (PMID 32824625, 2020). "Low brain-derived neurotrophic factor has been implicated in the pathophysiology of depression." (PMID 33269104, 2020). "It was verified that the Met allele of BDNF was significantly correlated with depression." (PMID 32281722, 2020). "In this study, BDNF was chosen as the downstream molecular target underlying the protecting effects of ARN-3236 against chronic stress, as BDNF is a very well-known member implicated in the pathogenesis of depression, and moreover, its biosynthesis is closely controlled by CRTC1 and CREB." (PMID 33519490, 2020). "Low levels of BDNF have been hypothesized to contribute to decreased neurobiological activity associated with depression." (PMID 32575733, 2020). "BDNF levels could be also influenced by a variety of factors including platelet count, gender, smoking status, depression, and age and Val66Met polymorphism." (PMID 31768951, 2020). "The reduced serum BDNF levels might be used as an early risk assessment marker for major depression." (PMID 32085720, 2020). "Recently, systematic reviews and meta-analyses of clinical studies suggest that BDNF is directly involved in the pathology of depression and that the restoration of BDNF may underlie the therapeutic efficacy of antidepressant treatment." (PMID 33265983, 2020). "Depression scores were negatively associated with serum BDNF levels in IFN-α−treated HCV patients." (PMID 32504419, 2020). "Epigenetic regulation of BDNF in stress-associated anxiety and depression is further discussed." (PMID 32085670, 2020). "Interestingly, genetic and epigenetic modifications in the BDNF gene have been associated to depressive disorders." (PMID 33066277, 2020). "Recently, the neurotrophic hypothesis of depression has attracted much attention, and the gene encoding for brain‐derived neurotrophic factor (BDNF) (OMIM: 113505) has become one of the most interesting candidate genes for MDD heritability and pathogenesis." (PMID 32869548, 2020). "Moreover, analyzed serum BDNF levels achieved good diagnostic value for drug-naive MDD patients which can be used as predictors for the assessment of depression risk." (PMID 32085720, 2020). "Depression models seem to show that both increased and decreased DA can affect the susceptibility to addiction, which makes us wonder whether the BDNF function is truly involved in the induction of addiction by depression." (PMID 32694984, 2020). "This is the first report of an association between religiosity and BDNF, that, among other effects, might be consider a biological marker of neuroplasticity in patients diagnosed with depression." (PMID 31572245, 2019). "Also, DNA methylation levels at the Brain-Derived Neurotrophic factor gene are associated with Major Depressive Disorder." (PMID 30875862, 2019).
depression (continued). "Also, activity-dependent BDNF release via endocytic pathways can be regulated by syt6 and complexin, which is closely linked to depression." (PMID 31024237, 2019). "Several studies have implicated BDNF levels in multiple brain areas with the pathophysiology of depression with decreased levels in the dentate gyrus and the CA3 of the hippocampus and prefrontal cortex or elevated levels in the nucleus accumbens promoting depressive phenotypes." (PMID 31749681, 2019). "Taking together with their important role in linking neuropsychiatric behaviors to synaptic plasticity, these results indicated that BDNF-related imbalance expression of Copine-6 and synapse plasticity-associated proteins play a vital role in the depression-like behavior induced by LPS challenge." (PMID 32009956, 2019). "To evolution whether the serum levels of BDNF are associated with depression in acne vulgaris patients, we conducted the multivariate logistic regression analysis." (PMID 31234814, 2019). "This process attenuates the neurogenesis effect of BDNF and causes depression." (PMID 31379957, 2019). "This suggested that changes in serum BDNF levels can reflect the changes of brain BDNF levels and may be associated with the pathophysiology of depression." (PMID 31234814, 2019). "Growing evidence has implicated that BDNF was strongly associated with depression." (PMID 30625977, 2019). "In summary, low BDNF levels seem to relate to depression and pre-treatment BDNF levels could be associated with ECT outcome." (PMID 31127089, 2019). "The neurotrophic hypothesis of depression proposes that depression is also accompanied by decreased neurotrophic support, which is primarily linked to the brain-derived neurotrophic factor (BDNF) protein." (PMID 31164818, 2019). "Furthermore, the relative signaling pathways of BDNF caused by early life stress have been studied to explore the mechanism of depression and antidepressants." (PMID 30984042, 2019). "The leading alternative to the monoamine hypothesis posits that depression relief is associated with elevations in hippocampal brain-derived neurotrophic factor (BDNF) (Duman and Monteggia, 2006; Castrén and Rantamäki, 2010)." (PMID 31708770, 2019). "HPA axis alteration in depression may inhibit neurogenesis, partly through reducing BDNF which is involved in hippocampal neurogenesis, thus possibly explaining one of the mechanisms by which depression may be a risk factor for AD." (PMID 30881301, 2019). "Depression contributes to alterations in various biochemical indexes, such as a deficiency of monoamine metabolites, an increased concentration of inflammatory factors, and a decreased level of BDNF in serum." (PMID 31569393, 2019). "Also, it was recommended that biological assessment of BDNF in early pregnancy is advantageous for risk prediction of antepartum depression." (PMID 31199848, 2019). "Inflammation reduces neuroplasticity by down-regulation of BDNF, which may underlies pathophysiology of depression." (PMID 31057357, 2019). "Because neuropsychiatric conditions such as depression are known to be associated with decreased BDNF expression, the comorbidity between dry eye syndrome and neuropsychiatric disorder may account for the observed BDNF dysregulation." (PMID 30833600, 2019). "The neurotrophic hypothesis suggests that pathological changes in brain areas associated with depression, are closely related to BDNF expression and functional down-regulation." (PMID 31231295, 2019). "Furthermore, there was an increased risk of depression associated with lower serum BDNF levels (OR: 0.52, 95% CI: 0.35–0.76; P < 0.05)." (PMID 31234814, 2019). "Further studies are needed to unravel the epigenetic regulation of BDNF expression and may reveal a more intricate interplay between DNA methylation and salivary BDNF in association with depression symptoms." (PMID 32038165, 2019).
depression (continued). "Furthermore, a significant decrease of the pro-BDNF and BDNF ratio in the hippocampus can cause the depression-like behaviors and alterations of CA1 pyramidal neurons." (PMID 31623364, 2019). "Preclinical and clinical studies have suggested that serum brain-derived neurotrophic factor (BDNF) levels increase after treatment with serotoninergic antidepressants, but the exact role of BDNF as a biomarker for diagnostic and treatment of major depression is still poorly understood." (PMID 31231276, 2019). "Therefore, As should be counted as an important risk factor for decreased early pregnancy BDNF level and risk of depressive disorders in pregnant women." (PMID 31199848, 2019). "A major reason for the large number of publications reporting on BDNF levels in serum is the intriguing association with numerous conditions including depression and neurodegenerative disorders such as Alzheimer’s disease, Parkinson’s disease, and Huntington’s disease." (PMID 29662942, 2018). "Activation of BDNF and TrkB is produced after administration of conventional antidepressant drugs, such as fluoxetine and citalopram, which is associated with the reduction of most of the symptoms of depression." (PMID 29623232, 2018). "Prolonged stress has been associated with region-specific changes in the expression of BDNF, synaptotagmin I, and synapsin I, and decreased BDNF has been associated with age-related hippocampal dysfunction, memory impairment, and increased risk for depression." (PMID 30429764, 2018). "According to the “neurotrophin hypothesis”, BDNF is critical for the limbic regions function associated with emotion processing and cognition in the development of depression." (PMID 30323763, 2018). "Likewise, deficiencies in ERK signaling are associated with depression, while antidepressants have been shown to upregulate both pERK and BDNF." (PMID 30200269, 2018). "Changes in BDNF have been associated with anxiety-related disorders and major depressive disorder." (PMID 30065945, 2018). "BDNF Val66Met could also increase the risk of AD-related depression and was associated with a better antidepressant response." (PMID 30337869, 2018). "Furthermore, through epigenetic evidences, BDNF reduction is also regarded as the susceptibility factor for depression, which involved in the development and plasticity of hippocampal nervous." (PMID 30323763, 2018). "Concerning the BDNF neuroprotective effects, it is possible that antidepressants that inhibit P38 in inflammation-associated depression may act by promoting BDNF cellular processes linked to neuroplasticity." (PMID 29867510, 2018). "As a neurotrophic factor that has been extensively associated with the pathophysiology of major depressive disorder, it is plausible that BDNF concentrations could mediate the relationship between selenium deficiency and depression." (PMID 29747386, 2018). "We also found that genetic variants in plasminogen activator inhibitor type 1 gene (encoded by the SERPINE1 gene), which is involved in the cleavage of pro-BDNF to mature BDNF in the brain, are related to antidepressant therapeutic response and depression susceptibility." (PMID 29725086, 2018). "Conversely, increased BDNF level has been associated with reduced symptoms of depression." (PMID 29465826, 2018). "The interaction between the synaptic vesicle-associated proteins and BDNF might trigger the imbalance of synaptic plasticity that occurs in depression." (PMID 30429764, 2018). "For example, increased BDNF activity in the ventral tegmental area-nucleus accumbens (VTA-NAc) pathway may be implicated in the pathogenesis of major depression." (PMID 29867348, 2018). "Indeed, BDNF and its epigenetic regulation have been associated with both the pathophysiology of depression and the mode of action of antidepressant treatments." (PMID 29353887, 2018).
depression (continued). "We found in a group of patients with severe depression that BDNF exon IV CpG-87 methylation was associated with higher remission rates, meaning that patients with a methylation at BDNF exon IV CpG-87 more often became remitter than patients without a methylation at BDNF exon IV CpG-87." (PMID 30459647, 2018). "Moreover, depression has been associated with alterations of growth factors, particularly in brain-derived neurotrophic factor (BDNF)." (PMID 30072893, 2018). "Brain-derived neurotrophic factor has been implicated in the pathogenesis of major depression." (PMID 29867348, 2018). "Recent studies investigating changes in neural plasticity associated with stress and depression suggested that BDNF might contribute to functional and structural adaptions of synapses in depression-related brain regions." (PMID 30367065, 2018). "BDNF plays an important role in hippocampal synaptic plasticity, neuronal migration, and protein synthesis-dependent long-term potentiation, and abnormal BDNF expression has been associated with depression and schizophrenia." (PMID 29966252, 2018). "Meanwhile, recent clinical studies indicated that BDNF might decrease the hippocampal volume and increase the risk of developing depression in those exposed to environmental stress or trauma." (PMID 29357818, 2018). "Synaptic vesicle-associated proteins are implicated in the regulation of BDNF-induced axonal growth and neurotransmitter release, and increasing evidence has demonstrated the relationship between synaptic dysfunction and depression." (PMID 30429764, 2018). "Similarly, the BDNF promoters’ DNA methylation changes of BDNF promoter I and promoter IV in brain has been demonstrated to be associated with major depression and suicide." (PMID 29636708, 2018). "In this study, post-mortem analyses showed that depressed patients also have lower BDNF levels in the anterior cingulate cortex (ACC) and the caudal brainstem compared to non-depressed subjects, providing further evidence implicating low brain BDNF and the BDNF Met allele in major depression risk." (PMID 29961124, 2018). "The BDNF Val66Met polymorphism has been reported to be associated with psychiatric disorders, including obsessive-compulsive disorder, schizophrenia, psychosis, major depression, anxiety, and eating disorders." (PMID 29867348, 2018). "The presence of brain-derived neurotrophic factor (BDNF) in human blood has generated considerable interest as illustrated by the very large number of publications associating BDNF levels with various conditions affecting brain function, including depression and neurodegeneration." (PMID 29662942, 2018). "Epigenetic alterations as DNA methylation, histone modifications, and non-coding RNAs are considered to be strongly associated with pathogenesis of depression with a large number of studies having examined the association between the BDNF methylation level and certain psychological diagnoses." (PMID 29636708, 2018). "Importantly, a low BDNF level is associated with post-stroke depression and acute stroke, and over-expression of BDNF in the hippocampus moderates depression behaviors in post-stroke depressive rats." (PMID 30319398, 2018). "Finally, increased brain-derived neurotrophic factor (BDNF) signaling in the Nacc has been linked to depression in humans, as well as greater susceptibility to the depressive effects of social defeat and diet-induced obesity in mice." (PMID 29910467, 2018). "Many clinical studies also found that BDNF levels were significantly lower in MDD patients than in controls, and decreased serum levels of BDNF in MDD patients recovered to normal levels associated with the recovery of depression after treatment with antidepressant medication." (PMID 29725086, 2018). "Moreover, during the depressive disorders development, BDNF is a critical factor associated with hippocampal neuronal plasticity and neuronal survival." (PMID 30323763, 2018).
depression (continued). "Likewise, changes in neural plasticity in terms of altered long-term potentiation or long-term depression have been observed in relation to the BDNF Val66Met polymorphism in the human brain as well as in animal models." (PMID 28824404, 2017). "Thus, despite the lack of evidence for the association between the risk of MDD and Val66Met in the BDNF gene due to a limited number of studies, Val66Met in BDNF gene has been considered to be associated with late-life depression." (PMID 29387021, 2017). "Besides epilepsy, BDNF is implicated in the pathogenesis and treatment of neuropsychiatric disorders such as major depression and autism spectrum disorder patients." (PMID 29358904, 2017). "It was reported that depression, which might be a manifestation of tumor brain and chemo brain in cancer patients, is often associated with reduced BDNF serum levels." (PMID 29179434, 2017). "The available evidence indicates that depression is tightly associated with alterations of microglia and inflammation, which manifested with more proinflammatory profile and decreased microglia-derived brain derived neurotrophic factor (BDNF)." (PMID 28694833, 2017). "In this sense, it is not possible to state that there is a causal pattern about sleep deprivation, BDNF and depression, but carefully examining all the studies in the field we can hypothesize it." (PMID 29299044, 2017). "Previous studies have found significant associations between serum BDNF and depression, and BDNF may even play an important role in the association between depression and CVD." (PMID 29028824, 2017). "Others have shown the association of BDNF gene polymorphism with anxiety and depression in asthma and thus suggested that genetic variants may assume a significant role in the pathogenesis of distress disorder in the context of asthma." (PMID 29217995, 2017). "Stress is hypothesized to cause a reduction in BDNF (protein) level in the brain, which alters mood and may cause depression." (PMID 29312105, 2017). "The aim of the current study was to examine the effect of the BDNF Val66Met polymorphism on behavioral despair at baseline, and whether a depression-like phenotype was unmasked or modulated by a history of chronic stress." (PMID 28926000, 2017). "Importantly, BDNF has been repeatedly implicated in the pathology of depression and antidepressant treatment." (PMID 29097744, 2017). "Mice exposed to stressors early in life show decreased CBP (which has HAT activity) and histone H3K9ac association with the BDNF IV promoter and decreased BDNF expression and neurogenesis inhibition in the hippocampus and increased anxiety- and depression-like behaviors in adulthood." (PMID 28360846, 2017). "Therefore, although there was evidence suggesting that Val66Met is associated with late-life depression, BDNF can be considered as a marker for the state of MDD rather than a trait marker for MDD." (PMID 29387021, 2017). "Reduced levels of BDNF or growth factors may be related to the structural and neural plastic changes associated with stress and depression because decreases in BDNF may cause neuronal death and atrophy; this factor is necessary for neuronal remodeling." (PMID 28446154, 2017). "The goal of this study was to elucidate the mechanisms that underlie the association between the ApoE genotype and depression by examining the three ApoE isoforms’ differential modulation of brain-derived neurotrophic factor (BDNF) signaling, serotonergic signaling, and synaptic function." (PMID 28934977, 2017). "The decrease in BDNF level associated with various diseases and depression suggest then that the decrease in BDNF concentration 24 h after exercise may be associated with increased central motor fatigue." (PMID 29312105, 2017). "The relationship between zinc and depression may be linked to its action on brain-derived neurotropic factor (BDNF), a growth factor promoting neurogenesis and differentiation." (PMID 28713269, 2017).